HGF (hepatocyte growth factor)
Diseases named in the same sentence as HGF in open-access papers (continued):
Sharing a sentence is not in itself a finding about the gene and the disease.
myeloma (continued). "Co-cultivation of the human myeloma cell lines ANBL-6 and JJN3 with bone marrow stromal cells or the HS-5 cell line resulted in a significant increase in secreted HGF." (PMID 24716444, 2014). "Since the number of the primary CD138+ cells in eight patient samples were insufficient for performing a detailed investigation of HGF/MET signaling, we decided to further investigate the effects of amuvatinib in a myeloma cell line." (PMID 24326130, 2013). "To elucidate in more detail the mechanism of action of amuvatinib in myeloma cells, we evaluated its effect on MET activity and downstream signaling in the myeloma cell line U266, which over-expresses HGF." (PMID 24326130, 2013). "Expression of both HGF and MET has been demonstrated in most myeloma cell lines and primary patient samples." (PMID 24326130, 2013). "BMSC further enhance the myeloma-induced immune dysfunction, by secreting factors such as VEGF, HGF, fibroblast growth factor (FGF), and stromal-cell-derived factor (SDF)-1α." (PMID 22567028, 2012). "Specifically, MEK is required for HGF-induced proliferation, whereas PI3K mediates myeloma cell rescue from apoptosis." (PMID 22567028, 2012). "Hepatocyte growth factor (HGF)/scatter factor was originally described as a factor promoting growth and scattering of multiple myeloma cells." (PMID 15846300, 2005). "This imbalance can be mediated directly by myeloma cells via the receptor activator of NF-B ligand (RANKL), hepatocyte growth factor (HGF) or interleukin (IL)-3, or indirectly via BMSC through the upregulation of RANKL and secretion of IL-6, IL-1β or tumor necrosis factor (TNF)-α." (PMID 36361677, 2022). "Furthermore, chemotherapy was found to potentially promote HGF/c-Met/IL-11 activation via SDC-1 shedding, exacerbating bone destruction in the setting of myeloma." (PMID 35118073, 2021). "Our previous study of inflammation in the context of myeloma and its asymptomatic stage (MGUS) revealed that except for four cytokines found to be significantly higher in myeloma (HGF, IL-11, RANTES, SDF-1α), the levels of 38 inflammation cytokines were similar in MGUS and in myeloma." (PMID 32872203, 2020). "Profiling for angiogenesis related cytokines of endothelial cells isolated from bone marrow of multiple myeloma patients treated with MP0250, confirmed that neutralization of VEGF and HGF results in a change of the cytokine profile towards in favor of antiangiogenic acting cytokines." (PMID 31575023, 2019). "An HGF/Met/IL-11/IL-6/gp130/STAT3 cascade was found to be activated in PV clonal erythroblasts; activation of a similar autocrine HGF/IL-11/IL-6 cascade has been described in multiple myeloma and in solid tumours." (PMID 25119536, 2014). "Our HGF gene expression profiling data reflect these findings as the observed HGF mRNA levels measured in CD138+ cells isolated from bone marrow aspirates of healthy individuals and myeloma patients at different disease stages varied widely within each sample group." (PMID 24716444, 2014). "In contrast, the drug did not induce apoptosis in another myeloma cell line (RPMI-8226/S) that is not dependent on the MET/HGF signaling axis due to lower levels of HGF (75% less) and MET (95% less)." (PMID 24326130, 2013). "While expression of both HGF and MET transcripts has been shown to be present in myeloma cells and HGF mRNA has also been demonstrated to be expressed in bone marrow stromal cells the levels of HGF and MET mRNA in patient plasma cells have not been well evaluated nor correlated with disease status." (PMID 24326130, 2013).
myeloma (continued). "Furthermore, a comparison of serum angiogenic markers Ang2, G-CSF, follistatin, HGF, FGF-1, endothelin 1, and VEGF-A has been carried out between Monoclonal gammopathy of undetermined significance (MGUS) and smouldering myeloma (SMM/MM) groups of patients (clinical trial NCT01237054)." (PMID 33808304, 2021). "If we accept these definitions, this suggests the possibility that the myeloma cells from our patients were not especially dependent on HGF/c-MET signaling and that selected patients with high HGF levels could have fared better." (PMID 28337527, 2017). "Furthermore, the ability of roneparstat to inhibit multiple myeloma growth and angiogenesis has been correlated with disruption of the heparanase/syndecan-1 axis and downregulation of HGF, VEGF and MMP-9 gene expression controlled by endogenous heparanase in myeloma cells." (PMID 27374103, 2016). "Hence the serum HGF levelhas been proposed as an independent prognostic marker in myeloma, in AML, andin CML but in MPNs, such studies have not yet been performed in large cohorts of patients." (PMID 25119536, 2014). "Interestingly, OPN did not correlate with HGF, suggesting an effect on different pathways in the regulation of both, angiogenesis, and myeloma proliferation regulation." (PMID 22629140, 2012). "Also in the myeloma cell lines OH-2 and IH-1 similar results were seen: HGF alone did not increase proliferation but potentiated the effect of IL-6, and likewise, incubation with IL-6 increased the expression of c-Met." (PMID 19187270, 2009). "Myeloma cells adhere to the stromal cells and induce secretion of OAFs including interleukin (IL)-6, IL-1, tumor necrosis factor (TNF), IL-11, macrophage inflammatory protein-1α (MIP-1α), hepatocyte growth factor (HGF), parathyroid hormone-related peptide (PTHrP), and others." (PMID 18577267, 2008). "Interestingly, we observed increased HGF production in co-cultures of BMSC with the cell lines ANBL-6 and JJN3, but not with other myeloma cell lines." (PMID 24716444, 2014). "The candidate enhancers of HGF and UCHL1 exemplify de novo formed enhancers, i.e., not present at any stage of late B lineage development, while the CCND2 enhancer provides an example of ‘re-commissioned’ super-enhancer, i.e., active in myeloma but not in normal PC." (PMID 34521827, 2021).
glioblastoma (84 papers, 2003 to 2025). The most malignant astrocytic tumor (WHO grade IV). "Hepatocyte growth factor (HGF), also known as scatter factor (SF), is a heparin-binding mesenchyme-derived cytokine that has been linked to glioblastoma multiforme (GB) angiogenic process." (PMID 38523646, 2024). "The activation of the hepatocyte growth factor/mesenchymal–epithelial transition (MET) pathway is implicated in the progression of glioblastoma, as it activates downstream signaling events including Ras/Raf/MAPK, STAT3, and PI3K/AKT/mTOR." (PMID 35743016, 2022). "The present study was to explore the potential effects of paeoniflorin on HGF-mediated migration, invasion, and actin cytoskeleton rearrangement as well as the underlying mechanism in glioblastoma." (PMID 30886866, 2019). "Taken together, paeoniflorin repressed HGF-mediated glioblastoma cells migration and invasion and caused actin rearrangement." (PMID 30886866, 2019). "The findings of an inhibitory effect on HGF/c-MET by TGF-β in vitro prompted us to validate an association between the two pathways in vivo using human glioblastoma specimens." (PMID 29238047, 2017). "This new method allowed us to monitor the dynamic changes in cell and tissue phosphorylomes associated with activation of the hepatocyte growth factor (HGF)/c-Met signaling relevant to malignancy, particularly glioblastoma multiforme." (PMID 24023761, 2013). "Migration of seven glioblastoma cell lines responded to HGF; the ligand of MET’s encoded Met." (PMID 40867621, 2025). "Additionally, coexpression of MET and its ligand HGF occur frequently in cancers, including glioblastoma, and have been associated with increased malignancy and decreased patient survival." (PMID 31245283, 2019). "Earlier studies of U87 and LN229 glioblastoma cell lines and a clinical specimen’s cells reported chemoattraction to HGF and serum." (PMID 40867621, 2025). "For T98G, HAE-M exhibited low selectivity at 48 h, with SI values of 1.32 (ARPE-19) and 0.53 (hGF), suggesting limited therapeutic potential against glioblastoma cells." (PMID 40005959, 2025). "CAFs in glioblastoma are able to enhance the proliferation of glioblastoma stem cells by expressing osteopontin and hepatocyte growth factor, as well as drive macrophage polarization towards the tumor-promoting type, mediated by fibronectin produced by CAFs." (PMID 40136652, 2025). "In the previous studies, we have demonstrated anti-tumor activity of the first kringle domain from hepatocyte growth factor (HGFK1) in glioblastoma and renal cell carcinoma." (PMID 36793021, 2023). "The hepatocyte growth factor (HGF)/MET signaling pathway has been proposed to be involved in the resistance to radiotherapy of glioblastoma via proinvasive and DNA damage response pathways." (PMID 36915128, 2023). "There is also increasing interest in the role of the HGF/MET pathway in the response of glioblastoma to radiotherapy." (PMID 36915128, 2023). "In the context of glioblastoma, invasion, scatter factor/hepatocyte growth factor (SF/HGF), and epidermal growth factor receptor (EGFR) act on cell motility." (PMID 35053605, 2022). "Another study shows that glioblastoma cells with activated HGF/SF–Met signaling were both proliferative and invasive, and these phenotypes appeared to activate distinct downstream signaling events, independently from each other." (PMID 35740514, 2022). "We tested the impact of the core cysteines in the HGF PAN domain on STAT3 activation by following its phosphorylation in glioblastoma U-87 MG and HeLa cells." (PMID 35778602, 2022). "SF/HGF and its receptor c-Met, which is a proto-oncogene product and has tyrosine kinase activity, promote cell motility in glioblastoma." (PMID 35053605, 2022). "Analysis of TCGA data demonstrated that about 30% of glioblastomas showed over-expression of HGF and MET." (PMID 35935338, 2022).
glioblastoma (continued). "More research has shown that MET and its ligand HGF play an important role in proliferation, survival, migration, invasion of angiogenic stem cells, drug resistance and recurrence of glioblastoma cells." (PMID 35935338, 2022). "Regarding glioblastoma, 89Zr-labeled nanobodies targeting HGF have demonstrated their theragnostic potential in preclinical models." (PMID 36585418, 2022). "Other factors, such as TGFβ, TNFα, IL6, HGF, EGF, and PDGF are also regulators and inducers of EMT and are all implicated in glioblastomas." (PMID 35053605, 2022). "The treatment of glioblastoma cells with Hepatocyte Growth Factor (HGF) resulted in cMET-AXL co-clustering, AXL phosphorylation at Y779, recruitment of ELMO-DOCK180 complex, RAC1 activation, reorganization of the cytoskeleton, and enhanced cell motility." (PMID 34638349, 2021). "GAMs and glioblastoma cells express hepatocyte growth factor/scatter factor (HGF/SF), which binds to c-Met tyrosine kinase and promotes proliferation and invasion of glioblastoma cells." (PMID 34485282, 2021). "For example, stimulation of human glioblastoma cells with HGF allows the cells to escape cell cycle arrest." (PMID 33066121, 2020). "Another potential predictive biomarker that should be considered in future trials of MET inhibitors in glioblastoma is HGF expression by the tumor, based on preclinical data." (PMID 31776899, 2020). "It has been reported that RhoG, activated by EGF and hepatocyte growth factor (HGF), contributes to the formation of lamellipodia and invadopodia and promotes glioblastoma cell migration and invasion." (PMID 32089990, 2020). "An increasing number of evidences have demonstrated that HGF played a key role in a variety of cancer progressions and accelerated the tumor-promoting activity including glioblastoma." (PMID 30886866, 2019). "In summary, our results demonstrated paeoniflorin inhibited HGF-mediated migration, invasion, and actin cytoskeleton rearrangement in glioblastoma cells." (PMID 30886866, 2019). "Earlier analyses of TCGA data showed that approximately 30% of glioblastomas display the overexpression of HGF and MET, suggesting that autocrine HGF activation can occur in the patient population." (PMID 31221203, 2019). "We found that APC- and biotin-conjugated anti-MET antibodies strongly induced MET and AKT phosphorylation, as compared to the HGF control, in all these glioblastoma cell lines." (PMID 30760737, 2019). "We observed that paeoniflorin inhibited HGF-induced migration and invasion and actin cytoskeleton rearrangement in glioblastoma cells." (PMID 30886866, 2019). "Several other molecules and axes associated with HGF/MET signaling have been found to contribute to the stem cell phenotype and aberrant vascularization of glioblastomas." (PMID 31221203, 2019). "In recent years, mounting evidence has suggested that the interactions between several other signaling pathways and the HGF/MET signaling pathway play a vital role in the pathogenesis of glioblastoma." (PMID 31221203, 2019). "In our present study, paeoniflorin suppressed HGF-mediated migration and invasion and actin cytoskeleton rearrangement of glioblastoma cells, and the mechanism involved c-Met/RhoA/ROCK1 signaling regulation." (PMID 30886866, 2019). "Nevertheless, TGF-β exerts an inhibitory effect on MET phosphorylation and suppresses HGF/MET pathway activity in glioblastoma." (PMID 31221203, 2019). "EGFRvIII induces the transactivation of JNK2 in glioblastoma cells, and then promotes increased cellular invasion through the stimulation of an HGF/MET signaling circuit." (PMID 31221203, 2019). "Regulation of MET expression by TGFβ1 seems to be tumor‐type‐specific as in glioblastoma, TGFβ suppresses HGF/MET pathway activity." (PMID 30004628, 2018). "Here we have elucidated the complex crosstalk between the TGF-β- and HGF-dependent signaling pathways in gliobastoma using three patient-derived GIC models as well as human glioblastoma specimens." (PMID 29238047, 2017).
glioblastoma (continued). "HGF stimulation of glioblastoma resulted in interactions of Dock7 and c-Met in a manner that is dependent on the adaptor protein Gab1, which also interacts with Dock7 in an HGF-dependent manner." (PMID 28475121, 2017). "Activation of its tyrosine kinase domain by binding of hepatocyte growth factor/ scatter factor (HGF/SF) in glioblastoma cells is thought to stimulate a more invasive phenotype and to promote tumor angiogenesis." (PMID 27043632, 2016). "In a glioblastoma xenograft cell model, elevated levels of mRNA HGF and cMET were detected in the mesenchymal subtype of glioblastoma, a more aggressive form of this disease." (PMID 27055285, 2016). "Other Rho-family GTPases have not yet been examined, but RhoG merits consideration since it has been reported to stimulate membrane ruffling and macropinocyctosis and can activate Rac1 in response to EGF or HGF in glioblastoma cells." (PMID 25762935, 2015). "MET, the tyrosine kinase receptor of HGF, is another potential target in different types of solid and hematological neoplasms, such as colorectal carcinoma, glioblastoma, and breast carcinoma." (PMID 28548076, 2014). "MetMab has been shown (10 μg/ml (100 nM) or higher) to inhibit cell migration in U87 glioblastoma, in a modified Boyden chamber assay, in the presence of 20 ng/mL of HGF." (PMID 24638075, 2014). "HGF also mediated migration of MSCs to sites of apoptotic cell death and towards HGF-expressing glioblastomas, and this observation has been exploited in gene therapy to deliver therapeutic drugs to the tumor cells." (PMID 24381939, 2013). "In search of a mechanism for the contribution of RhoG to the malignant behavior of glioblastoma cells, we found that depletion of RhoG strongly inhibits activation of the Rac1 GTPase by both HGF and EGF." (PMID 22966858, 2012). "A few studies have shown that HGF protects glioblastoma cells from DNA-damaging agents by activating PI3K/AKT anti-apoptotic pathways." (PMID 22741575, 2012). "Hsp90 inhibition by ansamycins has been reported to suppress cancer cell motility and invasion through depletion of the HGF/c-Met signaling pathway in both leiomyosarcoma and glioblastoma cell lines." (PMID 20828379, 2010). "In contrast, AKT activated by HGF partially inhibited the Taxol-induced apoptosis in Taxol-responsive human U373 glioblastoma cells." (PMID 12644839, 2003). "To anticipate and study specific resistance mechanisms associated with targeting this pathway, we engineered resistance to the HGF-neutralizing antibody rilotumumab in glioblastoma cells harboring autocrine HGF/Met signaling, a frequent abnormality of this brain cancer in humans." (PMID 36672409, 2023). "The changes in the cytoskeleton that we observed may be the result of a reduced HGF level, which has been demonstrated to affect the distribution of the actin cytoskeleton in glioblastoma cell lines." (PMID 35702951, 2022). "In addition, EGFRvIII is able to induce trans-activation of JNK2 in glioblastoma cells and then to promote increase of invasion of cell by stimulating the HGF/MET signaling circuit." (PMID 35935338, 2022). "DOCK7-controlled migration can also be pathological; it was identified to be required for human hepatocyte growth factor (HGF)-induced glioblastoma tumor cell invasion, with upregulated DOCK7 found in astrocytoma human glioblastoma compared with nonneoplastic brain." (PMID 33684443, 2021). "Additionally, DOCK 7 is reported to play a critical role in the invasive behavior of the glioblastoma and mediates Rac1 activation following HGF stimulation." (PMID 32089990, 2020). "In addition, in an in vivo model of a human glioblastoma xenograft with a PTEN mutation and HGF expression (presumably leading to autocrine MET activation), the combination of these two agents was significantly more efficacious than either agent alone." (PMID 31776899, 2020).